CD4 (CD4 molecule)
Diseases named in the same sentence as CD4 in open-access papers (continued):
Sharing a sentence is not in itself a finding about the gene and the disease.
hepatitis B (129 papers, 2008 to 2025). "The pooled estimate of the reviewed literature showed that ART patients with a CD4 count <200 cells/μL were 3.54 (1.12–11.21) times more at risk for infection with hepatitis B than those who had a CD4 count >500 cells/μL." (PMID 40255371, 2025). "In a multivariate Cox model that adjusted for age, CD4+ count > or < 250/mm3 and hemoglobin level, the presence of hepatitis B or C remained significantly associated with the development of liver toxicity of any grade (hazard ratio [HR]: 1.797, 95% CI 1.042-3.098, P = 0.035)." (PMID 24708626, 2014). "The panel recommended broadening options for starting ART at a CD4 count above 350 cells/mm3 and to include people with active hepatitis B or C infection, cardiovascular disease risk, or compromised kidney function The panel set no upper CD4 limit on when treatment should begin." (PMID 19811670, 2009). "Users of 3TC+TDF have a favorable profile regarding virological suppression and CD4+ T lymphocyte response; it is an interchangeable regimen with low rates of relative risk and few resistant strains that can also be administered in cases of hepatitis B coinfection." (PMID 35371095, 2022). "A similar immunosuppressive role is seen in chronic viral infections, such as hepatitis B and C. IL-35-producing CD4+ T cells and B cells are elevated in hepatitis B, potentially contributing to viral persistence and chronicity." (PMID 40869939, 2025). "In hepatitis B, elevated levels of IL-35-producing CD4+ T cells and B cells have been observed, implicating the cytokine in immune modulation and viral persistence." (PMID 40869939, 2025). "Three studies compared CHM plus drugs to drugs alone, which involving 399 patients and two viral infectious dieases (hepatitis B and viral myocarditis), reported both CD4 and CD8 T lymphocytes levels." (PMID 38512808, 2024). "The case was a man who had sex with men on ART with an undetectable HIV viral load and 368 CD4 + cells/mm3, with serological markers of past hepatitis B virus (HBV) infection (positive for HBV anti-core and anti-surface antigen (HBsAg) antibodies)." (PMID 38095070, 2024). "The expression level of FANCD2 significantly correlated with the infiltration levels of Treg cells, B cells, CD8 + T cells, CD4 + T cells, neutrophils, macrophages, myeloid dendritic cells, and NK cells in Hepatitis B-related HCC." (PMID 37821996, 2023). "This study was aimed to determine the oral bacterial profile of HIV-positive patients and their correlation with T lymphocyte and CD4 count and hepatitis B and C incidence." (PMID 35783688, 2022). "Comorbidities were present in 408 (61.4%) and only 21 (3.2%) participants were co-infected with hepatitis B. Median CD4 count and viral load at diagnosis were 178 cells/mm3 (IQR 57–341) and 77,000 copies/ml (IQR 21,248–252,252) respectively." (PMID 34706742, 2021). "Immunofixation electrophoresis showed a marked increase in IgG and IgM, free lambda, and free kappa/free lambda ratio with HIV viral load of 39,400 copies/ml, absolute CD4 count of 56, and an acute hepatitis B panel." (PMID 34557371, 2021). "The frequency and number of TSCMs was affected by hepatitis B virus infection, possibly because of the relative balance between the consumption and production of CD4+ T cells in patients with hepatitis B infection included in this study." (PMID 34327142, 2021). "The odds of having hepatitis B virus infection among pregnant women with CD4 less than 200, from 200–350, and 351–499 cells/mm3 was much higher than women with CD4 greater than 500 cells/mm3." (PMID 33930097, 2021). "One animal study investigated the therapeutic effect of vitamin D3 combined with interferon on mice with hepatitis B. The percentage of CD4+ and the CD4+/CD8+ ratio was significantly increased, but the percentage of CD8+ was reduced." (PMID 32316365, 2020). "The second are HIV replication, AIDS status, hepatitis B and C coinfection, low CD4 nadir, lipodystrophy and ART." (PMID 31430930, 2019).
hepatitis B (continued). "TDF causes kidney damage in 1–5% of the cases, principally in patients with pre-existing renal disease, risk factors for CKD, concomitant use of potentially nephrotoxic agents, a low CD4 T-cell count and viral hepatitis B and/or C." (PMID 31430930, 2019). "Those who were hepatitis B positive, were more likely to be male (52.6%) versus (36.4%) (P < 0.0001) and to have a lower median CD4 count at hepatitis B test (423 cells/μL) (IQR 269–600) versus 483 cells/μL (IQR 325–657)." (PMID 30288326, 2018). "With the combination of the MPL and QS-21, vaccines using the AS01 adjuvant have been shown to elicit strong antigen-specific polyfunctional CD4+ T-cell responses against multiple pathogens including varicella-zoster and hepatitis B." (PMID 29698406, 2018). "Hepatitis B positive had lower CD4 count: 423 cells/μL, (IQR: 269–600) compared to hepatitis B negative patients 483 cells/μL (IQR:325, 657), p value < 0.0001)." (PMID 30288326, 2018). "Younger participants too were more likely to have missing hepatitis B and hepatitis C results, whereas older participants are likely to have missing BMI and CD4 results." (PMID 27562473, 2016). "In this study, FACS analysis of a large number of patient samples revealed a discrete distribution of CD39 expressing CD4+ T cells in healthy controls and hepatitis B patients, which were discernable by their levels of CD39 expression." (PMID 22489829, 2012). "However, being born before the universal implementation of routine hepatitis B immunisation and CD4 count < 350 cells/mL predicted HBsAg positivity in a Sierra Leone study." (PMID 37891471, 2023). "CD4 count and haematological parameters (HPs) could be used to monitor the health status of hepatitis B (HB) individuals." (PMID 37545948, 2023). "Second, there could have been residual confounding from unmeasured patient characteristics that affected the CD4 response (i.e. seroconversion date, hepatitis B or C infection, ART)." (PMID 31905222, 2020). "Both CD8+ CTL and CD4+ Th cells are essential for therapeutic hepatitis B vaccines." (PMID 25689855, 2015). "Analogous to what is known from hepatitis B and C, iTregs may be induced (possibly at the expense of conventional CD4+ effector T cells) to dampen effector responses directed at CMV-infected endothelium." (PMID 24203779, 2014). "When determining the expression of IL-23R in PBMCs of patients with CHB by flow cytometry (FCM) analysis, we also found that most IL-23R+ cells were IL-17+CD4+ T cells, which indicated that the circulating Th17 cells expressed a high level of IL-23R under the hepatitis B condition." (PMID 23825942, 2013). "Characterization of the TCR repertoire of CD4+CD25+ Treg subsets from hepatitis B patients may clarify its role in ACLF pathogenesis." (PMID 22978653, 2012). "Polymorphisms in the genes involved in stimulating the activation and proliferation of CD4+ T helper cells may influence the immune response to hepatitis B vaccination." (PMID 22536368, 2012). "For example, elevated TGF-β in patients with hepatitis B might "tune" CD4+ T cells with increased sensitivity to IL-6R signaling through inhibition of SOCS3." (PMID 21639870, 2011). "Hepatitis B vaccine-induced immunity is promoted by the presentation of HBsAg via HLA class II molecules on antigen-presenting cells to CD4 T helper cells, thereby triggering HBsAg-specific B cells to proliferate and differentiate into anti-HBs producing cells (primary immune response)." (PMID 18365030, 2008). "Although it is not well-understood whether hepatitis B can cause CD4+ T cell depletion, the immune mechanism of patients with progressive damage due to chronic infection is clear." (PMID 34327142, 2021). "Although much knowledge regarding this enigmatic disease remains unclear, researchers have identified some common immune responses in hepatitis B. For example, various immune cell types play a role in the development of acute and chronic hepatitis, including NK, CD4+ T, and CD8+ T cells." (PMID 27994596, 2016).
hepatitis B (continued). "The findings suggested that molecules involved in the activation of CD4+ Th cells might influence the efficacy of hepatitis B vaccination, and contributed to a better understanding of the diversity and complexity of the genetic factors that affect the efficacy of hepatitis B vaccination." (PMID 22536368, 2012). "CD32, an Fc‐gamma receptor IIa (FcγR‐IIa), has been associated with activated CD4+ T cells and its persistent expression has been reported in CD4+ and CD8 + T cells of individuals with chronic infections such as hepatitis B." (PMID 41204857, 2025). "We found a positive correlation between FANCD2 expression and Tregs, B cells, CD4 + T cells, CD8 + T cells, neutrophils, and macrophage infiltration in Hepatitis B-related HCC." (PMID 37821996, 2023). "CD4+CXCR3-CCR4-CCR6- Th9 cells were purified from PBMCs of seven CHB patients and nine hepatitis B-related HCC patients, as well as from IHLs of six hepatitis B-related HCC patients (HCC specimens and non-tumor site liver specimens)." (PMID 34177894, 2021). "Other parameters possibly influencing the CD4+ cell recovery are the CD8+ cell count or the CD4+/CD8+ ratio, co-infections as Hepatitis B or Hepatitis C or the treatment regimen used to initiate cART." (PMID 33537915, 2021). "In mice, the administration of anti-CD25 mAbs to deplete Tregs enhanced CD4 and CD8 T cell responses to BCG and hepatitis B vaccines, and preexisting CD4+CD25+ Tregs suppressed BCG responses in vitro and in vivo." (PMID 28855899, 2017). "In hepatitis B positive patients, it has been reported that CD4+ cells were less frequent but not CD8+ cells." (PMID 34585256, 2022). "Differences in the frequency and absolute value of CD4+ lymphocyte subsets in patients with or without Hepatitis B." (PMID 34327142, 2021). "Adjustment for adherence, hepatitis B, and baseline CD4 count did not change this result (adjusted odds ratio [aOR] 2.88, 95% CI 0.13–62.95, P=0.50)." (PMID 25878720, 2015). "Our finding of only 2% of women with occult hepatitis B (as defined by detectable HBV DNA with a negative HBsAg) is lower than reported from some studies that had sicker participants with lower CD4 counts." (PMID 24855985, 2014). "All subjects in VTCs with more than 2 members were Hepatitis B/Hepatitis C negative and had similar ranges of CD4 and viral loads." (PMID 24586911, 2014). "In one study, individuals with occult hepatitis B (HBV DNA present in the absence of hepatitis B surface antigen) demonstrated lower CD4 cell counts as compared to individuals without occult hepatitis B." (PMID 26316953, 2013). "Examining CD4+CD25+ Treg TCR diversity may further our understanding of peripheral tolerance mechanisms and the role peripheral Tregs, and how this applies to hepatitis B patients." (PMID 22978653, 2012). "We did make substantial efforts to control for potential confounders using available subject metadata, but acknowledge that for many subjects, data were not available for other potential confounders such as hepatitis B or C coinfection, socioeconomic factors, or current and nadir CD4 T cell counts." (PMID 38316748, 2024). "Expansion of the IFNγ− population in the spleen upon boosting with H1Y98F-VLP but not the H1WT-VLP is reminiscent of the CD4+ T cell responses to protein vaccines such as hepatitis B, diphtheria and tetanus, that are dominated by Thpp cells and elicit robust and durable antibody responses." (PMID 35410323, 2022). "ALHIV who revealed their risk for HIV transmission as intravenous drug users, those had WHO stage 3 and 4, those without documented CD4 cell count test, hepatitis B and C test results at enrolment and those whose haemoglobin was <10 gm/dl had higher hazards of attrition during the ART time periods." (PMID 31364536, 2019).
hepatitis B (continued). "Thus the significant change in the CD4 T count recorded among the study participants prior to TLE/ZLE administration within 5 months was independent of age, gender, comorbidities (TB and hepatitis B infections), and baseline CD4 and CD8 cell counts." (PMID 29850480, 2018). "Using triple fluorescence staining, we confirmed that CD39 and FoxP3 expressions co-localized within regions with partial CD4+ T cells, indicating that the CD4+FoxP3+CD39+ Treg cells did exist in the portal area of liver tissue and might be involved in hepatitis B pathogenesis." (PMID 22489829, 2012). "Therefore, conserved TCRBV gene families may help produce antibody specific to TCRBV motifs, inhibiting the corresponding CD4+CD25+ Tregs and aiding hepatitis B treatment." (PMID 22978653, 2012). "Interestingly and important for therapy development, during a hepatitis B flare, TNFα- and IFNγ-producing HBV-specific CD4+ T cells could be detected, further indicating that the CD4+ T cells still poses the capability of type I cytokine production when re-activated." (PMID 34066322, 2021). "In general, cytotoxic mechanisms for HBV-specific CD4+ and CD8+ T cells and noncytotoxic mechanisms for IFN-γ and TNF-α, which are produced by natural killer (NK) cells, are detectable in acute hepatitis B patients." (PMID 33670625, 2021). "CD4+CXCR3-CCR4-CCR6- Th9 cells were purified from PBMCs of seven CHB patients and seven hepatitis B-related HCC patients, as well as from IHLs of six hepatitis B-related HCC patients (HCC specimens and non-tumor site liver specimens)." (PMID 34177894, 2021). "The significant change in the CD4+ count recorded among the study participants prior to TLE/ZLE administration was found to be independent of age and HIV comorbidities (TB and hepatitis B infections)." (PMID 29850480, 2018). "In contrast to the response observed after infection, the majority of vaccine-induced CD4+ T cells had a phenotype of IL-2+TNF-α+IFN-γ- cells similar to responses observed with other non-live vaccines, such as hepatitis B or tetanus." (PMID 26465323, 2015). "Since 2011, the treatment was given to patients with CD4 cell count of less than 350 cells/mm3, with the exception of pregnant women with HIV, babies born from women with HIV, and PLHIV with TB and Hepatitis B who are not yet on ART (these PLHIV received ART regardless of their CD4 cell count)." (PMID 26424195, 2015).
Cirrhosis (125 papers, 2011 to 2026). A chronic disorder of the liver in which liver tissue becomes scarred and is partially replaced by regenerative nodules and fibrotic tissue resulting in loss of liver function. "A study from Spain, which included almost 2400 people, reported both cirrhosis and a CD4+ cell count < 200 to be associated with increased odds of unsuccessful treatment in multivariable analysis." (PMID 39656170, 2025). "Another German study found that baseline CD4+ cell count less than 350, CD4% < 20 and cirrhosis were associated with unsuccessful treatment in univariable analysis; however, only cirrhosis was statistically significant in multivariable analyses." (PMID 39656170, 2025). "Hepatitis E virus (HEV) poses significant health concerns worldwide, particularly among people living with HIV (PLWHIV), due to an increased risk of chronic infection and progression to cirrhosis in individuals with low CD4 cell counts." (PMID 39057763, 2024). "Meanwhile, the presence of fibrosis/cirrhosis was also associated with a lower B cell allostimulatory capacity, manifested in the reduced ability of alloreactive CD4+ T cells producing the antifibrotic factor after the B-cell contact." (PMID 37143511, 2023). "Alcoholism, hepatic cirrhosis, and lower nadir CD4 count were associated with the risk of death in patients with IPD." (PMID 37368746, 2023). "Alcoholism (p = 0.018), hepatic cirrhosis (p = 0.003), and lower nadir CD4 count (p = 0.033) were associated with the risk of death in patients with IPD." (PMID 37368746, 2023). "The presence of cirrhosis was also associated with a lower B cell allostimulatory capacity, manifested in the reduced ability of alloreactive CD4+ T cells to produce TNFα and TNFβ after B cell contact." (PMID 33036244, 2020). "The experimental results showing that RT leads to the death of HIV‐infected CD4 T cells are basically the same as our experimental results, in which the RT domain of HBp causes the death of hepatocytes, leading to cirrhosis and HCC." (PMID 29321963, 2018). "In univariate analysis, excessive alcohol consumption, estimated time duration from HCV infection, nevirapine and lopinavir-based ARV regimen and CD4 nadir were associated factors of extensive fibrosis/cirrhosis." (PMID 27148964, 2016). "In our previous work, reduction of CD27+ B-cell frequency in cirrhosis was strongly associated with reduced B-cell cytokine production as well as impaired allostimulation-induced CD4+ T-cell proliferation." (PMID 27857173, 2016). "These could be related cirrhosis-associated chronic hepatic and systemic inflammation leading to the activation and differentiation of T cells, resulting in a decrease naïve CD4 + T cells." (PMID 38369527, 2024). "The presence of cirrhosis was negatively associated with an increase of CD4+ cell count." (PMID 25775475, 2015). "The presence of cirrhosis was negatively associated with a CD4+ T cell count increase." (PMID 25775475, 2015). "A similar trend was observed for CD4+ T cells, where TNFα expression was downregulated after stimulation with IL-12 + IL-18 in compensated cirrhosis compared to healthy controls." (PMID 41028194, 2025). "Taken together, these data demonstrate that higher salt intake in patients with compensated cirrhosis specifically promotes Th17-mediated responses, shifting the balance of CD4+ helper subsets towards Th17 inflammation." (PMID 40705454, 2025). "Our study investigated the impact of dietary salt intake on CD4+ T cell responses and clinical parameters in patients with compensated cirrhosis." (PMID 40705454, 2025). "In clinical tissues, miR‐500a‐3p is significantly enriched in HCC and cirrhosis tissues, and co‐expression of the immune marker CD4 or PD‐L1 significantly correlates with low survival rates in patients." (PMID 39574357, 2025).